ZNF71 (zinc finger protein 71)
Description:
May be involved in transcriptional regulation.
Synonyms: EZFIT; Cos26
Tractability: PROTAC: ubiquitination databases record sites on it.
Gene: Protein-coding gene on chromosome 19 (56,595,265 to 56,626,481, forward strand). Ensembl gene ENSG00000197951.
Subcellular location: Nucleus
Subcellular location (Human Protein Atlas): Nucleoli; Nucleoplasm
Pathways (Reactome):
Gene expression (Transcription): Generic Transcription Pathway
Gene Ontology:
Molecular function: protein binding; DNA-binding transcription activator activity, RNA polymerase II-specific; RNA polymerase II cis-regulatory region sequence-specific DNA binding
Biological process: regulation of transcription by RNA polymerase II; positive regulation of transcription by RNA polymerase II
Cellular component: nucleus
Genetic constraint (gnomAD): Loss-of-function variants: 2 observed, 2.25 expected, observed/expected ratio (o/e) 0.89, 90% interval 0.34 to 1.85. That is too few expected variants to judge how well the gene tolerates losing a copy. Missense variants: 684 observed, 729.89 expected, observed/expected ratio (o/e) 0.94, 90% interval 0.88 to 1. Synonymous variants: 340 observed, 310.15 expected, observed/expected ratio (o/e) 1.1, 90% interval 1 to 1.2.
Homologues: Orthologues: macaque ZNF71 (97% identical), chimpanzee ZNF71 (88% identical), dog ZNF71 (80% identical), pig ZNF71 (78% identical). Paralogues in human: ZNF571 (40% identical), ZNF605 (38% identical), ZNF33B (38% identical), ZNF30 (37% identical), ZNF841 (37% identical), ZNF568 (37% identical), ZNF7 (37% identical), ZNF658 (37% identical), ZNF182 (36% identical), ZNF300 (36% identical), ZNF836 (36% identical), ZNF484 (36% identical), and 164 more.
Diseases named in the same sentence as ZNF71 in open-access papers:
ZNF71 is named in the same sentence as 14 diseases in open-access papers, as found by Europe PMC text mining. Sharing a sentence is not in itself a finding about the gene and the disease. The quoted sentences say what the papers report.
asthma (2 papers, 2013 to 2023). "For instance, novel IgE-related genes (CRIM1, ZNF71, TLN1, and SYNPO2) were uncovered by the only GWAS of IgE in asthma patients." (PMID 37761964, 2023). "Instead, this study identified additional candidate genes (CRIM1, ZNF71, TLN1, SYNPO2, etc.)for total serum IgE levels in asthma patients." (PMID 23967269, 2013).
non-small cell lung carcinoma (2 papers, 2021 to 2022). A group of at least three distinct histological types of lung cancer, including non-small cell squamous cell carcinoma, adenocarcinoma, and large cell carcinoma. "As a member of the family, ZNF71 expression is associated with chemical sensitivity, and protein expression correlates with the prognosis of non-small cell lung cancer (NSCLC)." (PMID 36369089, 2022). "Our previous study found that zinc finger protein 71 (ZNF71) mRNA expression was associated with chemosensitivity and its protein expression was prognostic of non-small-cell lung cancer (NSCLC)." (PMID 33916522, 2021).
adenosquamous carcinoma (1 paper, 2021). A carcinoma composed of malignant glandular cells and malignant squamous cells. "Adenosquamous carcinoma had the highest ZNF71 KRAB expression." (PMID 33916522, 2021).
large cell carcinoma (1 paper, 2021). A malignant epithelial neoplasm composed of large, atypical cells. "In the studied cell lines, large cell carcinoma had the highest ZNF71 overall expression." (PMID 33916522, 2021).
lung adenocarcinoma (1 paper, 2022). A carcinoma that arises from the lung and is characterized by the presence of malignant glandular epithelial cells. "We found that overexpression of ZNF71 in A549 lung adenocarcinoma cells resulted in the downregulation of multiple components of the intracellular intrinsic and innate immune systems, including dsRNA (OAS1) and dsDNA (STING, pTBK1) sensors and viral restriction factors (TRIM5, SAMDH1)." (PMID 36499305, 2022). "To investigate the potential function of ZNF71 in intracellular immune response, we overexpressed its KRAB and KRAB-less isoforms in lung adenocarcinoma A549 cells." (PMID 36499305, 2022).
oral squamous cell carcinoma (1 paper, 2023). "A study on oral squamous cell carcinoma showed that the co-expression gene of zinc finger protein 71 (ZNF71) was mainly enriched in the HSV1 infection pathway." (PMID 37396042, 2023).
oropharyngeal cancer (1 paper, 2015). Carcinoma, predominantly squamous cell, arising from the epithelial cells of the oropharynx. "All but ZNF14 are located on the 19q13 locus, which was shown to be epigenetically silenced in oropharyngeal cancer, supporting the hypothesis that ZNF160, ZNF420, ZNF585B, and ZNF71 are epigenetically regulated in a coordinated fashion." (PMID 26544568, 2015).
squamous cell carcinoma (1 paper, 2021). A carcinoma arising from squamous epithelial cells. "Squamous cell carcinoma had the lowest expression of both ZNF71 overall and KRAB isoform (Figure A2)." (PMID 33916522, 2021).
tumor (5 papers, 2015 to 2022). "The association between ZNF71 and its isoforms in terms of chemoresponse is also complex due to different genetic predisposition to chemotherapeutic regimens in tumor cells." (PMID 33916522, 2021). "The results showed that the expression of ZNF71 was positively correlated with tumor-infiltrating lymphocytes, such as neutrophils, activated dendritic cells, type 17 helper cells, and monocytes." (PMID 36369089, 2022). "We further evaluated the relationship between ZNF71 expression and immune cells and stromal cells in the tumor immune microenvironment (TME) through the ESTIMATE algorithm." (PMID 36369089, 2022). "Overall, the observed overexpression of the ZNF71 KRAB isoform in tumor cells resistant to docetaxel and paclitaxel treatment compared to chemo-sensitive cells is consistent with its negative association with patient survival in NSCLC." (PMID 33916522, 2021). "We analyzed ZNF71 isoform expression in the RNA-seq dataset GSE81089 of NSCLC tumor samples (n = 197) and correlated the analysis with patient outcomes." (PMID 33916522, 2021). "In the studied NSCLC cell line panel, ZNF71 KRAB overexpression was observed in tumor cells that were resistant to Taxol compared to Taxol-sensitive tumor cells." (PMID 33916522, 2021). "All but ZNF71 demonstrated significant downregulation of expression in tumor samples compared to normal tissues, which was consistent with increased methylation levels." (PMID 26544568, 2015). "Downregulation of ZNF71 may promote LSCC development by reducing the tight junction between tumor cells and reducing immune infiltration." (PMID 36369089, 2022). "Furthermore, based on the TISIDB online tool, we further analyzed the relationship between ZNF71 expression and 28 kinds of tumor-infiltrating lymphocytes." (PMID 36369089, 2022). "The expression of ZNF71 KRAB and KRAB-less isoforms was significantly correlated in both patient tumor samples (p < 8.6 × 10−15, Pearson’s correlation) and cell lines (p < 2.3 × 10−8, Pearson’s correlation)." (PMID 33916522, 2021). "Twenty candidate genes (84%) showed methylation in greater than 50% of primary tumor, including ADFP, FUZ, ZNF71, ENPP5, ZNF211, and ZNF14." (PMID 26544568, 2015). "Of all remaining five ZNF protein genes, ZNF14, ZNF160, ZNF71, ZNF420 and ZNF585B, DNA methylation was significantly higher in tumor samples, as compared to normal controls." (PMID 26544568, 2015). "The ZNF71 KRAB isoform (ZNF71_203_ENST00000599599) had a significantly higher expression (p < 0.001, t-tests) than the KRAB-less isoform (ZNF71_201_ENST00000328070) in NSCLC patient tumor samples (n = 197) and cell lines (n = 117)." (PMID 33916522, 2021). "The absence of ZNF71 may promote LSCC progression by reducing the tight junction between tumor cells and reducing immune infiltration." (PMID 36369089, 2022). "Normalized ZNF71 dependency scores were not significant (below the threshold of –0.5) in the NSCLC cell lines in either RNAi (processed with DEMETER2) or CRISPR-Cas9, indicating that a knockdown/knockout of ZNF71 did not significantly affect NSCLC tumor cell growth in vitro." (PMID 33916522, 2021). "Therefore, we speculated that the absence of ZNF71 may promote LSCC development by reducing the tight junctions between tumor cells." (PMID 36369089, 2022). "ZNF71 was absent in different LSCC subpopulations, including cancer cells, plasma cells, and tumor-infiltrated immune cells, based on scRNA-seq analysis." (PMID 36369089, 2022).
cancer (3 papers, 2022 to 2024). A tumor composed of atypical neoplastic, often pleomorphic cells that invade other tissues. "Based on the function of structurally relevant KRAB-ZNFs, we hypothesized that ZNF71 could be involved in the suppression of endogenous transposable elements (TEs) expression, which is often activated in cancer and can trigger an innate immune response." (PMID 36499305, 2022). "Based on its structure-inferred function, we hypothesized that ZNF71 could be involved in the suppression of endogenous transposable elements (TEs) expression, which is often activated in cancer and can trigger an innate immune response." (PMID 36499305, 2022).
ZNF71 also shares sentences with these, for which no sentence is quoted: airway hyperresponsiveness (1 paper); emphysema (1); laryngeal squamous cell carcinoma (1); osteosarcoma (1).